FGD5-AS1 (FGD5 antisense RNA 1)
Gene: Long non-coding RNA gene on chromosome 3 (14,920,347 to 14,948,424, reverse strand). Ensembl gene ENSG00000225733.
Diseases named in the same sentence as FGD5-AS1 in open-access papers:
FGD5-AS1 is named in the same sentence as 3 diseases in open-access papers, as found by Europe PMC text mining. Sharing a sentence is not in itself a finding about the gene and the disease. The quoted sentences say what the papers report.
osteosarcoma (1 paper, 2022). A usually aggressive malignant bone-forming mesenchymal neoplasm, predominantly affecting adolescents and young adults. "Meanwhile, RNA pull-down assay, along with luciferase reporter and RNA immunoprecipitation (RIP) assays, was utilized to detect the interaction G3BP2, miR-124-3p and FGD5 antisense RNA 1 (FGD5-AS1) may exert on the regulation of osteosarcoma cells." (PMID 35761386, 2022).
cancer (1 paper, 2023). A tumor composed of atypical neoplastic, often pleomorphic cells that invade other tissues. "Through analysis of all m6A regulators frequency across 33 cancer types in TCGA, it was found that a well‐known lncRNA, FGD5 antisense RNA 1 (FGD5‐AS1), had the second‐highest correlativity among all m6A regulators." (PMID 35789547, 2023).
tumor (1 paper, 2021). "FGD5 antisense RNA 1 (FGD5-AS1) is identified as a significant tumor regulator in malignancies." (PMID 34692852, 2021).